MSH6 (mutS homolog 6)
Diseases named in the same sentence as MSH6 in open-access papers (continued):
Sharing a sentence is not in itself a finding about the gene and the disease.
prostate carcinoma (continued). "In the MSH6 non-carrier control cohort, under a scenario of a 100% biopsy compliance rate, the prostate cancer incidence would then be 0·6% (one of 177; 95% CI 0·0–3·1; vs 3·0% [four of 135; 0·8–7·4] in MSH6 carriers), with a difference in incidence of 2·4% (0·7–5·5; p=0·17)." (PMID 34678156, 2021).
glioma (42 papers, 2006 to 2025). A benign or malignant brain and spinal cord tumor that arises from glial cells (astrocytes, oligodendrocytes, ependymal cells). "Haematological cancers were common among PMS2 or MSH6 mutation carriers, while gastrointestinal and CNS cancers were prevalent across all four MMR genes." (PMID 39247025, 2024). "Increased chemosensitivity to TMZ in MSH6-inactivated gliomas and overcoming acquired chemoresistance caused by MMR deficiency have been reported." (PMID 37169803, 2023). "Germline mutations of MSH6 are known to cause high susceptibility to glioma, as well as a number of benign or malignant tumors in other organs." (PMID 35370679, 2022). "Although these tumours are deficient in DNA MMR and harbour high mutational burdens, recent single-centre studies suggest post-temozolamide MSH6 mutated hypermutant gliomas are poorly responsive to CPI therapy." (PMID 33631295, 2022). "Acquired mutations, particularly in the DNA mismatch repair gene MSH6, are common in gliomas after treatment with temozolomide." (PMID 33631295, 2022). "MSH6 knockdown increases temozolomide resistance and somatic mutations in MSH6 are associated with temozolomide resistance in gliomas." (PMID 32066500, 2020). "MSH6 mutation status (wild type or mutant) was also assessed because mutations are frequently seen in high-grade gliomas that recur after treatment with TMZ and RT, and because MSH6 mutations are known to mediate TMZ resistance." (PMID 30153289, 2018). "Glioma treated with TMZ acquires somatic MSH6 mutations, conferring TMZ resistance and resulting in a hypermutational process which supports rapid evolution of clones with growth advantage." (PMID 30248992, 2018). "Recent studies have reported that MSH6 mutations are considered to play an important role in the recurrence of glioma, acquired resistance to alkylating agents and genome instability." (PMID 29871594, 2018). "The clinical relevance of MSH6 heterogeneity in iCCA is underlined by studies reporting resistance to alkylating agents in gliomas due to MSH6 mutation." (PMID 28146430, 2017). "Recently, MSH6 mutations have been demonstrated to arise in gliomas as a consequence of treatment with temozolomide, and have been implicated in drug resistance and the presence of a hypermutated phenotype." (PMID 21637783, 2011). "Interestingly, recent preclinical data showed restoration of TMZ sensitivity specifically in MSH6-deficient glioma cells using PARPi." (PMID 33216206, 2021). "Several studies have suggested that loss of MSH6 activity confers resistance to temozolomide treatment in glioma and may therefore contribute to progressive tumor growth and tumor recurrence." (PMID 24073290, 2013). "To model primary TMZ resistance, we generated GBM cell lines with CRISPR-induced knockout of MSH6, which encodes a DNA mismatch repair gene frequently mutated in TMZ-resistant glioma." (PMID 36989359, 2023). "Its mutational analysis identified previously identified hereditary gene changes such as MSH6 known to confer susceptibility to glioma, BRCA1 germline mutation which is extremely rare in gliomas, as well as a novel mutation EWSR1 in glioma." (PMID 35370679, 2022).
glioma (continued). "In particular, MSH6 (MutS homolog 6) is a DNA mismatch-repair protein that has been identified as a putative driver gene in glioma." (PMID 32082376, 2019). "Defects in MMR are associated with TMZ resistance of glioma cells and chronic exposure to TMZ can produce resistant clones harboring MSH6 mutations." (PMID 30248992, 2018). "It has been recently reported that MSH6 alterations arise in gliomas as a consequence of temozolomide treatment." (PMID 24073290, 2013). "Taken together, this suggests that rs1800932 is an eQTL for increased expression of MSH6 in gliomas, which may increase sensitivity to temozolomide, the primary chemotherapeutic agent for gliomas." (PMID 32066500, 2020). "Here, we investigated whether the MMR pathway were involved in XIST/miR-29c regulation of glioma cell chemoresistance to TMZ by measuring the protein levels of MSH6, MGMT, and SP1." (PMID 28831025, 2017). "Scant data are available on MMR complex proteins in high-grade gliomas, and deficit of expression of MSH6 might contribute to alkylating agent resistance and recurrence; despite that, the role of MMRd in terms of survival in this setting of patients seems unclear." (PMID 32937743, 2020). "In the present study, we monitored the protein levels of MSH6, MGMT, and SP1 in response to cotransfecting XIST and miR-29c in TMZ-resistant glioma cell lines." (PMID 28831025, 2017). "The driver genes such as MSH6 and RUNX1T1 might serve as candidate prognostic biomarkers and therapeutic targets in glioma." (PMID 29046615, 2017). "DNA repair protein O6-methylguanine-DNA methytransferase (MGMT) plays a key role in TMZ resistance; transcription factor specificity protein 1 (SP1), a regulator of DNA mismatch repair (MMR) key protein MSH6, has been reported to be up-regulated in TMZ-resistant glioma cell lines." (PMID 28831025, 2017). "The driver genes and pathways identified herein such as MSH6 and RUNX1T1 might be candidate prognostic biomarkers and therapeutic targets in glioma." (PMID 29046615, 2017). "Finally, consistent with prior studies in established glioma cell lines, knockout of MSH6 in primary GBM cultures induced resistance to TMZ, but not KL-50." (PMID 41169667, 2025).
gastric cancer (34 papers, 2007 to 2025). A primary or metastatic malignant neoplasm involving the stomach. "Furthermore, they identified one MSH6-positive gastric cancer infiltrating lesion with a complete loss of the MSH6 expression in its heterogeneous hyperplastic lesion; however, both regions were MSI-H and had the same MSH6 variant:c.3261delC." (PMID 36591511, 2022). "We might miss out MSI cases with the isolated loss of PMS2 or MSH6, although those may be exceptional, at the least, in gastric carcinomas." (PMID 32498695, 2020). "By contrast, MSH6’s low expression level was significantly linked with poor FP (P=0.019), OS (P=6e-04) and PPS (P=1.7e-05) prognosis in patients with gastric cancer." (PMID 34941572, 2021). "The proportion of gastric cancer in MSH6 carriers was higher than normal in the general population but the difference was not statistically significant." (PMID 30386444, 2018). "Our study demonstrates that MLH1-/PMS2-/MSH6- digestive system cancer cases are a rare subgroup of dMMR cancers, that account for 1.4% of all cases in our cohort and do not only occur in CRCs but also in ampullary as well as gastric cancer." (PMID 36387226, 2022). "MSH6 expression in gastric carcinoma, a coincidental cancer in this case, was intact." (PMID 32611331, 2020). "Of 8 cases of gastric cancer in the MSH6 cohort, the age at diagnosis could be confirmed for 6 and 4 of these (67%) occurred before age of 50 years." (PMID 30386444, 2018). "In gastric cancer, the MLH1-/PMS2- pattern was observed in 93.3% of cases, followed by PMS2- (3.3%), and MLH1-/MSH6-/PMS2- (3.3%)." (PMID 37953261, 2023).
glioblastoma (34 papers, 2012 to 2026). The most malignant astrocytic tumor (WHO grade IV). "In our study, TMB varied from 0 to 18 mut/Mb, with a median value of 3 mut/Mb, but one primary glioblastoma sample with MSH6 mutations had TMB equal to 82 mut/Mb." (PMID 39684714, 2024). "Both of these glioblastomas with heterozygous MSH6 mutations had low somatic mutation burden with TMB values of less than 5 mutations per Mb, and both were microsatellite stable with instability at less than 2% of the 86 evaluated microsatellites." (PMID 38079020, 2023). "MSH6 mutations have been described as a mechanism of tumor resistance to TMZ treatment in glioblastoma." (PMID 36157469, 2022). "Loss of MSH6 expression in glioblastoma post treatment is one mechanism for acquired resistance to TMZ." (PMID 35892832, 2022). "Contrary to the loss of MSH6, a recent study in glioblastoma found increased expression of MSH6, which was associated with TMZ resistance." (PMID 30274152, 2018). "This acquired resistance to alkylating chemotherapy secondary to MMR MSH6 gene mutation was rescued by downstream peroxisome proliferator-activated receptor (PPAR) inhibition of DNA repair—a targeted therapy for TMZ-resistant recurrent glioblastoma." (PMID 38928445, 2024). "In glioblastoma multiforme, MSH6 can affect the tumor microenvironment by regulating HIF1A to accelerate tumor metastasis." (PMID 38879468, 2024). "Msh6 participates in a feedback loop, Msh6-CxcR4-Tgfb1, that promotes glioblastoma formation, proliferation, migration, and invasion." (PMID 38139447, 2023). "To evaluate the cellular phenotype of MSH6 loss and the resulting TMZ resistance in GBM cells, we reduced the expression of MSH6 (knockdown, KD) using shRNA or mutated the MSH6 gene (knockout, KO) using the CRISPR/Cas9 system in LN428 glioblastoma cells." (PMID 35892832, 2022). "Previous studies have suggested similar trends with respect to NER components, while alterations in MMR genes such as MSH6 have been associated with TMZ resistance and recurrent glioblastoma tumours." (PMID 35406779, 2022). "Combining a BER inhibitor (PARP inhibitor) with TMZ was found to induce G2/M arrest, an increase in double-strand DNA breaks, and elevated apoptosis in MSH6-deficient, TMZ-resistant glioblastoma cells." (PMID 35892832, 2022). "In Case-76 (glioblastoma, 12 years) a heterozygous, de novo 1 bp insertion within MSH6, leading to a frameshift and a preterminal stopcodon (p.(Gly1105Trpfs*3)) was detected." (PMID 33840814, 2021). "Importantly, recurrent glioblastomas acquire new mutations following initial chemoradiation, including mutations in DNA mismatch repair (MMR) genes MSH6, MLH, and LTBP4." (PMID 38928445, 2024). "Accordingly, this review first aims to summarize current research in recurrent glioblastoma such as the molecular pathways and genetic mutations that drive cell proliferation (TERT, PTEN, PI3K/Akt, MSH6, and LTBP4) and paracrine signaling of glioma stem cells (GSCs)." (PMID 38928445, 2024). "However, it is proposed in glioblastoma that high MSH6 promotes aggressive cell phenotypes more directly by acting through a MSH6-CXCR4-TGFβ1 feedback loop that regulates p-STAT3/Slug and p-Smad2/3/ZEB2 signalling pathways." (PMID 36482191, 2023).